KCNQ5 (potassium voltage-gated channel subfamily Q member 5)
Description:
Pore-forming subunit of the voltage-gated potassium (Kv) channel broadly expressed in brain and involved in the regulation of neuronal excitability. Associates with KCNQ3/Kv7.3 pore-forming subunit to form a potassium channel which contributes to M-type current, a slowly activating and deactivating potassium conductance which plays a critical role in determining the subthreshold electrical excitability of neurons. Contributes, with other potassium channels, to the molecular diversity of a heterogeneous population of M-channels, varying in kinetic and pharmacological properties, which underlie this physiologically important current. Also forms a functional channel with KCNQ1/Kv7.1 subunit that may contribute to vasoconstriction and hypertension. Channel may be selectively permeable in vitro to other cations besides potassium, in decreasing order of affinity K(+) = Rb(+) > Cs(+) > Na(+). Similar to the native M-channel, KCNQ3-KCNQ5 potassium channel is suppressed by activation of the muscarinic acetylcholine receptor CHRM1.
Synonyms: Kv7.5; MRD46
Tractability: Small molecule: an approved drug acts on it; a high-quality ligand is known; it belongs to a druggable protein family. Antibody: UniProt places it where antibodies can reach, with high confidence; its Gene Ontology location is reachable by antibodies, with high confidence; UniProt predicts a signal peptide or a membrane-spanning region. PROTAC: ubiquitination databases record sites on it; its protein half-life has been measured; a small molecule that binds it is known.
Target class: Potassium channels; Ion channel; Voltage-gated ion channel; Voltage-gated potassium channel
Safety:
Unwanted effects reported when the protein is acted on. In parentheses: how it was acted on, where the effect was seen, and who reports it.
diarrhea (source: ClinPGx)
Gene: Protein-coding gene on chromosome 6 (72,621,792 to 73,198,853, forward strand). Ensembl gene ENSG00000185760.
Subcellular location: Cell membrane
Subcellular location (Human Protein Atlas): Cytoplasmic bodies
Pathways (Reactome):
Neuronal System: Voltage gated Potassium channels
Gene Ontology:
Molecular function: protein binding; voltage-gated potassium channel activity; monoatomic ion channel activity
Biological process: potassium ion transmembrane transport; monoatomic ion transport; potassium ion transport; transmembrane transport
Cellular component: clathrin coat; plasma membrane; voltage-gated potassium channel complex; membrane
Genetic constraint (gnomAD): Loss-of-function variants: 21 observed, 72.54 expected, observed/expected ratio (o/e) 0.29, 90% interval 0.2 to 0.42. The upper end of that interval is the gene's LOEUF score, 0.42, which puts it in group 1 of 6, group 1 being the genes least tolerant of losing a copy. Missense variants: 695 observed, 961.56 expected, observed/expected ratio (o/e) 0.72, 90% interval 0.68 to 0.77. Synonymous variants: 374 observed, 364.77 expected, observed/expected ratio (o/e) 1.03, 90% interval 0.94 to 1.12.
Homologues: Orthologues: chimpanzee KCNQ5 (99% identical), macaque KCNQ5 (99% identical), dog KCNQ5 (98% identical), rabbit KCNQ5 (97% identical), mouse Kcnq5 (96% identical), rat Kcnq5 (95% identical), pig KCNQ5 (94% identical), guinea pig KCNQ5 (91% identical), tropical clawed frog kcnq5 (78% identical), zebrafish kcnq5b (61% identical), zebrafish kcnq5a (61% identical). Paralogues in human: KCNQ2 (43% identical), KCNQ4 (43% identical), KCNQ3 (38% identical), KCNQ1 (27% identical), KCNB2 (14% identical), KCNA3 (11% identical), KCNC3 (11% identical), KCNA4 (10% identical), KCNC2 (10% identical), KCND1 (10% identical), KCNA5 (10% identical), and 19 more.
Diseases named in the same sentence as KCNQ5 in open-access papers:
KCNQ5 is named in the same sentence as 90 diseases in open-access papers, as found by Europe PMC text mining. Sharing a sentence is not in itself a finding about the gene and the disease. The quoted sentences say what the papers report.
epilepsy (13 papers, 2011 to 2025). A brain disorder characterized by episodes of abnormally increased neuronal discharge resulting in transient episodes of sensory or motor neurological dysfunction, or psychic dysfunction. "Lehman and colleagues reported four individuals suffering from ID and/or epilepsy caused by KCNQ5 variants, which they described as LOF and one GOF (P369R) carried by the most severely affected individual." (PMID 36088682, 2022). "In particular, Kcnq5 and Scn8a are both expressed only in cPNs and implicated in epilepsy and/or hyperactivity." (PMID 34188164, 2021). "However, it is interesting to note that they contain genes associated with disease in humans and dogs including epilepsy (KCNQ5), cancer (NPM1, FGR), and autoimmune disease (IL6)." (PMID 22022279, 2011). "This suggests that specific dysfunction of the KV7.3/KV7.5 channel may be associated with some forms of ASD, ID, major depression, epilepsy, and possibly other psychiatric disorders and accordingly KCNQ5 should also be considered a candidate gene for these disorders." (PMID 23596459, 2013). "Accordingly, KCNQ3 and KCNQ5 (OMIM 607357) are suggestive susceptibility genes for ASD, ID, major depression, epilepsy, and due to the considerable overlap in etiologies also for other psychiatric disorders like ADHD, bipolar disorder, and anxiety disorder." (PMID 23596459, 2013). "Similarly, Kcnq5 gain-of-function variants are associated with intellectual disability with or without epilepsy but no breathing phenotypes have been reported." (PMID 38052789, 2023). "A number of THC target DEGs were also associated with synaptic signaling in the brain, and the onset of epilepsy and intellectual deficits, including RPH3A, KCNQ5, and FRY." (PMID 41402937, 2025). "Our results suggest that dysfunction of the heteromeric KV7.3/5 channel is implicated in the pathogenesis of some forms of autism spectrum disorders, epilepsy, and possibly other psychiatric disorders and therefore, KCNQ3 and KCNQ5 are suggested as candidate genes for these disorders." (PMID 23596459, 2013).
myopia (10 papers, 2013 to 2025). "The rs7744813 SNP in intron 1 of KCNQ5 (NM_019842.4) has been associated with myopia by multiple independent GWAS meta-analyses." (PMID 36737489, 2023). "The association of KCNQ5 with refractive error and myopia has been identified by genome wide association study and further verified by our previous study." (PMID 35002772, 2021). "Regrettably, the protective effect of KCNQ5 alleles against high myopia still remains poorly understood and requires further investigations to explore its underlying mechanisms." (PMID 28884119, 2017). "Haplotypic analyses were performed here to help understand the effects of KCNQ5 gene polymorphisms on the manifestation of high myopia." (PMID 28884119, 2017). "This study provides new evidence of associations between potassium channel gene KCNQ5 and high myopia susceptibility." (PMID 28884119, 2017). "Overall, the present study shed new light on the implication of common KCNQ5 gene variants in the genetic susceptibility to high myopia and the potential role of potassium channels mediating ocular growth and myopic development." (PMID 28884119, 2017). "Our data support the involvement of KCNQ5 gene polymorphisms in the genetic susceptibility to high myopia and further exploration of KCNQ5 as a risk factor for high myopia." (PMID 28884119, 2017). "Validation of the role of KCNMA1 in myopia progression is needed, particularly in ion channel activity which is one of the major functional pathways implicated, with an existing pool of several associated genes (KCNQ5, KCNJ2, and CACNA1D)." (PMID 31415580, 2019). "Five tag single-nucleotide polymorphisms (SNPs) of KCNQ5 were genotyped, and association testing with high myopia was conducted using logistic regression analysis adjusted for sex and age to give Pasym values, and multiple comparisons were corrected by permutation test to give Pemp values." (PMID 28884119, 2017). "The KCNQ5 gene is believed to participate in the transport of potassium ions from the retina to the choroid and affect the function of cone and rod photoreceptors associated with myopia." (PMID 28884119, 2017). "This study investigated the role of potassium channel gene (KCNQ5) polymorphisms in high myopia." (PMID 28884119, 2017). "We found a significantly increased axial length and myopic shift in refractive status in three of our studied mutants, indicating a potential involvement of the human orthologs (LAMA2, LRRC4C, and KCNQ5) in myopia development." (PMID 36737489, 2023). "Lastly, our group investigated the associations with myopia progression and PRSs of SNPs in six genes—ZC3H11B, ZFHX1B, KCNQ5, SNTB1, GJD2 and MET—among Chinese children in Hong Kong." (PMID 35327754, 2022). "The aim of this study was to investigate the expression of potassium channel gene KCNQ5 and the changes of K+ microenvironment within the retina of form deprivation myopia (FDM) guinea pigs." (PMID 35002772, 2021). "KCNQ5 (potassium voltage-gated channel KQT-like subfamily, member 5), identified as myopia-related gene for the first time, encodes a potassium channel found in the retinal pigment epithelium (RPE) and neural retina." (PMID 28884119, 2017). "This region of KCNQ5 gene deserves further exploration and replication in different populations for a better understanding of the etiopathogenesis of myopia." (PMID 28884119, 2017). "The same study indicated that GJD2 and KCNQ5 may affect myopia progression through axial elongation." (PMID 39062192, 2024). "Future studies using KCNQ5 (Kv7.5)-selective potassium channel openers or inhibitors may lead to the discovery of new myopia treatments." (PMID 36737489, 2023). "These vQTLs are strong candidates for having either GxE or GxG interaction effects and, indeed, genetic variants located near the GJD2, LAMA2, RBFOX1, KCNQ5 and LRRC4C genes were associated with a progressively increasing risk of myopia as the number of years of schooling rose." (PMID 36395078, 2022).
myopia (continued). "In a guinea pig myopia model, retinal Kcnq5 gene and protein expression were down-regulated." (PMID 36395078, 2022). "Collectively, our study indicated that KCNQ5 may participate in form-deprivation myopia, but the specific mechanisms remain to be further studied." (PMID 35002772, 2021). "It suggested that KCNQ5 may play a role in the process of myopia, and the intervention of potassium channels may contribute to the prevention and control of myopia." (PMID 35002772, 2021). "Given that KCNQ5 encodes a potassium channel found in the RPE and neural retina, it is speculated that it may be involved in the ion transport mechanism underlying myopia." (PMID 35002772, 2021). "Furthermore, both retinal KCNQ5 expression and IK(M) decreased after induction of myopia with form deprivation, indicating the KCNQ5 involvement in myopia development in the guinea pig." (PMID 35002772, 2021). "Further in vivo drug intervention experiments may help improve the mechanism of KCNQ5 involvement in myopia." (PMID 35002772, 2021). "In order to explore the specific pathways of KCNQ5 involved in myopia, we focused on the role of KCNQ5 in potassium ion transport, and speculated that it might affect the development of myopia by regulating the potassium ion transport state in the retina." (PMID 35002772, 2021). "KCNQ5 is suggestively associated with myopia, but its specific role in the myopic process has not been studied further." (PMID 35002772, 2021). "Therefore, we conducted a case-control study to investigate the relationship between high myopia and SNPs in the potential hotspot region of the KCNQ5 gene." (PMID 28884119, 2017). "Replications in multiple populations indicated that KCNQ5 gene may play a crucial role in the development of myopia." (PMID 28884119, 2017). "Based on the regulation of KCNQ5 on the potassium microenvironment, we speculated that the change of KCNQ5 might affect the potassium ion homeostasis and M-current characteristics in the retina, thereby playing a role in myopia." (PMID 35002772, 2021). "Among them, it is noteworthy that two largest GWAS of myopia and refractive error, reported by 23andMe and Consortium for Refractive Error and Myopia (CREAM), discovered coincidentally a number of significant genome-wide associations, including the novel KCNQ5 gene with functions in ion transport." (PMID 28884119, 2017).
colorectal cancer (5 papers, 2018 to 2022). A primary or metastatic malignant neoplasm that affects the colon or rectum. "Sensitivities of methylated KCNQ5 and methylated C9orf50 in stool DNA for detecting colorectal cancer (CRC) in different genders, age groups, stages, tumor locations, tumor sizes, and differentiation statuses." (PMID 33585248, 2020). "Some miRNAs found in our analysis that regulate MYOC, KCNQ5, MUC1, and F3 mRNAs has been also described in other cancers, such as colorectal cancer cells and identified as biomarkers in lung cancer, osteosarcoma, ovarian cancer and penile cancer." (PMID 36012492, 2022). "Three DNA methylation markers, C9orf50, KCNQ5, and CLIP4, can discriminate between the plasma from colorectal cancer patients and that of healthy individuals." (PMID 33575272, 2020). "Three DNA methylation markers, C9orf50, KCNQ5, and CLIP4, were identified, each capable of discriminating plasma from colorectal cancer patients and healthy individuals (areas under the curve 0.86, 0.91, and 0.88)." (PMID 31727158, 2019). "Indeed, KCNQ5 and SPG20 were found to be downregulated in colorectal cancer compared to the normal mucosa due to promoter hypermethylation." (PMID 29670109, 2018). "Aberrant DNA methylation has emerged as a class of promising biomarkers for early colorectal cancer (CRC) detection, but the performance of methylated C9orf50 and methylated KCNQ5 in stool DNA has never been evaluated." (PMID 33585248, 2020).
Intellectual disability (5 papers, 2020 to 2024). "More recently, de novo heterozygous missense and truncating variants in KCNQ5 in individuals with intellectual disability (ID) alone or with DEE have been described." (PMID 36088682, 2022). "De novo missense variants in KCNQ5, encoding the voltage-gated K+ channel KV7.5, have been described to cause developmental and epileptic encephalopathy (DEE) or intellectual disability (ID)." (PMID 36088682, 2022).
adenoma (3 papers, 2019 to 2021). A neoplasm arising from the epithelium. "They target CpG sites located in the 5′-regions of the genes C9orf50, KCNQ5, and CLIP4 that were found to be concurrently hypermethylated in CRC and adenoma tissues, but unmethylated in blood cells and in most other cancer types." (PMID 31727158, 2019).
Epileptic encephalopathy (3 papers, 2020 to 2024). A condition in which epileptiform abnormalities are believed to contribute to the progressive disturbance in cerebral function. "Loss-of-function (LoF) and gain-of-function variants in KCNQ5 have been shown to cause epileptic encephalopathy." (PMID 32386536, 2020).
Hypertension (3 papers, 2016 to 2023). The presence of chronic increased pressure in the systemic arterial system. "Aloperine, a component of Sophora flavescens and an activator of KCNQ5, has been reported to relax mesenteric-resistant arteries and attenuate hypertension-associated vascular remodeling." (PMID 36980233, 2023). "KCNQ5 was recently reported to be a hypertension-associated gene in the mesenteric arteries of spontaneously hypertensive rats." (PMID 36980233, 2023).
schizophrenia (3 papers, 2010 to 2024). A major psychotic disorder characterized by abnormalities in the perception or expression of reality. "For instance, mutations in three genes our MR analyses linked to schizophrenia (RERE, KCNQ5) or anorexia (SUOX), respectively, are reported to cause monogenic diseases." (PMID 33417599, 2021). "What is more, KCNQ5 is connected to phosphoinositide signaling through regulation by PIP5K2A(MIM 603140), a schizophrenia-associated gene." (PMID 20808825, 2010). "Our MR results suggest that inhibition of RERE and KCNQ5 could be used to treat schizophrenia and GPNMB to treat Parkinson’s disease whereas promotion of SUOX could be used to treat Anorexia and ACE to treat Alzheimer’s disease." (PMID 33417599, 2021). "MR further suggests that KCNQ5 inhibitors could be re-purposed to treat schizophrenia." (PMID 33417599, 2021).
Alzheimer disease (2 papers, 2021 to 2024). A progressive, neurodegenerative disease characterized by loss of function and death of nerve cells in several areas of the brain leading to loss of cognitive function such as memory and language.
bipolar disorder (2 papers, 2010 to 2013). A disorder of the brain that causes unusual shifts in mood, energy, activity levels and the ability to carry out day-to-day tasks. "KCNQ5 (potassium voltage-gated channel subfamily KQT member 5) may contribute to episodic disturbances of mood and behavior as well-characterized roles in other ion-channelopathies, and two family members, KCNC2 and KCNQ2, were found to be associated with bipolar disorder." (PMID 20808825, 2010).
Obesity (2 papers, 2022 to 2024). Accumulation of substantial excess body fat. "The KCNQ5 gene encoding the KV7.5 channel is linked to the susceptibility to obesity in the Korean population." (PMID 39273144, 2024).
autosomal dominant mental retardation-46 (1 paper, 2020). "Interestingly, loss of function mutations in KCNQ5 have been shown to cause autosomal dominant mental retardation-46 (MRD46)." (PMID 32144193, 2020).
blood pressure (1 paper, 2023). "Mutations in dystrophin in VSMCs lead to significantly increased expression of KCNQ5 and RYR2, potentially resulting in low blood pressure in DMD patients." (PMID 37569835, 2023).
congenital diaphragmatic hernia (1 paper, 2020). A posterolateral defect of the diaphragm that allows passage of abdominal viscera into the thorax, leading to respiratory insufficiency and persistent pulmonary hypertension with high mortality. "Likewise, a markedly diminished KCNQ5 expression was found in the pulmonary vasculature of congenital diaphragmatic hernia fetuses." (PMID 32676036, 2020). "A recent study showed that the expression of KCNQ5, but not that of KCNQ1 or KCNQ4, was significantly downregulated at the mRNA and protein levels in rat lungs from nitrofen-induced congenital diaphragmatic hernia." (PMID 32676036, 2020).
diabetic neuropathy (1 paper, 2022). A chronic, pathological complication associated with diabetes mellitus, where nerve damages are incurred due to diabetic microvascular injury involving small blood vessels that supply these nerves, resulting in peripheral and/or autonomic nerve dysfunction. "Five of them, KCNA2, KCNA4, KCNQ5, KCNN1 and KCNS1, were also negative for screening in a diabetic neuropathy population." (PMID 36430572, 2022).
gastric cancer (1 paper, 2022). A primary or metastatic malignant neoplasm involving the stomach. "Furthermore, a 153 cfDNA methylation biomarker panel including DOCK10, CABIN1, and KCNQ5 was identified in a GC patient cohort, providing a novel method to diagnose early-stage gastric cancer." (PMID 36302755, 2022).
genetic generalized epilepsies (1 paper, 2022). "We set out to identify disease-related KCNQ5 variants in genetic generalized epilepsy (GGE) and their underlying mechanisms." (PMID 36088682, 2022).
glomerular disease (1 paper, 2014). "Proceeding from our data supporting the link between RANK and glomerular disease, further attempts seem necessary to elucidate the biological background of SNPs near KCNQ5 and FHIT for renal impairment." (PMID 25478860, 2014).